SSTR5 (somatostatin receptor 5)
Diseases named in the same sentence as SSTR5 in open-access papers (continued):
Sharing a sentence is not in itself a finding about the gene and the disease.
corticotroph adenomas (17 papers, 2010 to 2025). "Assessment of somatostatin receptor in corticotrope adenomas had revealed that SSTR5 is the most abundant receptor isoform." (PMID 32183012, 2020). "This way we were able to show that SSTR5 expression was exceptionally high in corticotroph adenomas, while there were only a few samples that had low expression rates or none at all." (PMID 30627156, 2018). "Recurrent CD cases showed a significantly higher expression of SSTR1 (p = 0.0351) and SSTR4 (p = 0.0174) while SSTR5 ID scores were lower than in primary corticotroph adenomas (p = 0.0370)." (PMID 30627156, 2018). "Pasireotide is a novel somatostatin analogue with high affinity for receptor subtypes 1, 2, 3, and particularly 5 (SSTR5), which was shown to be strongly overexpressed in corticotroph adenoma cells." (PMID 27034666, 2016). "We observed that SSTR5 is reduced in recurrent corticotroph adenomas indicating that their expression may be dynamically regulated." (PMID 30627156, 2018). "The demonstration that SSTR5 is highly expressed in the majority of human corticotroph adenomas and is more resistant to glucocorticoid down-regulation, has led to the development of the novel somatostatin analogues, notably pasireotide that binds SSTR1, 2, 3 and, with maximal affinity, SSTR5." (PMID 27086313, 2016). "Pasireotide is a second-generation somatostatin receptor ligand (SRL) with the highest affinity for somatostatin receptor subtype 5 (SSTR5), the most abundantly expressed SSTR in corticotropinomas." (PMID 40283624, 2025). "While SSTR2 and SSTR4 were not detectable in corticotroph adenomas, one out of three cases showed expression of SSTR1 and one out of two for SSTR3 and SSTR5." (PMID 30627156, 2018). "RT-PCR and IHC of five corticotroph adenomas congruently showed no detection of SSTR3 and SSTR4 while mRNA and IHC levels for SSTR5 were high." (PMID 30627156, 2018).
somatotropinomas (15 papers, 2018 to 2025). "In the study by Iacovazzo et al21 that included 39 patients with somatotropinomas, SSTR5 expression predicted responsiveness to pasireotide." (PMID 35602875, 2022). "SSTR5 is also expressed in abundance on somatotropinomas, providing rationale for the use of pasireotide in patients uncontrolled on SSTR2-preferential first-generation somatostatin analogues." (PMID 32217809, 2020). "Pasireotide has shown to be more effective in lowering GH levels than octreotide in tumors with relatively high SSTR5 expression, and a higher SSTR5 expression has been found in somatotropinomas to be poorly responsive to octreotide." (PMID 32121432, 2020). "In somatotropinomas, SSTR5 was the predominant SSTR subtype detected, followed by SSTR2, SSTR3 and SSTR1." (PMID 29266696, 2018). "In somatotropinomas, the expression levels of SSTR5 were positively correlated with SSTR2 (r = 0.49, Spearman FDR adjusted P < 0.0001) and SSTR3 (r = 0.28, P = 0.03)." (PMID 29266696, 2018). "In somatotropinomas, a higher expression of the SSTR2 gene was associated with higher efficacy of octreotide compared with pasireotide, whereas tumors with a higher level of SSTR5 tended to respond better to pasireotide." (PMID 34205778, 2021). "In somatotropinomas, resistance to SSA has been related to high expression of the truncated isoform of the SSTR5 (sst5TMD4)." (PMID 40259920, 2025). "Two other researchers’ groups found that in somatotropinomas and normal pituitary glands, the mRNA transcripts and proteins of SSTR2 and SSTR5 were expressed in all samples." (PMID 39202532, 2024). "While somatotropinomas primarily express both SSTR2 and SSTR5, which mediate their response to first-generation somatostatin analogs or Pasiroetide, the expression profile in corticotroph tumors is more heterogeneous and involves a predominant expression of SSTR5." (PMID 40364036, 2025).
Hyperglycemia (12 papers, 2015 to 2025). An increased concentration of glucose in the blood. "The increase in the lean mass and fat mass in the compound‐1‐treated group could be caused to enhance insulin action in tissues by reduction of hyperglycemia and hyperinsulinemia toxicity by SSTR5 inhibition." (PMID 36585794, 2023). "The pathophysiology underpinning PAS-induced hyperglycemia depends on its higher affinity for SSTR5 than SSTR2." (PMID 35744057, 2022). "It has high affinity for SSTR-1, SSTR-2, SSTR-3 and most importantly SSTR-5 and presents hyperglycemia as a common adverse effect, but experience in malignant INSs is very limited." (PMID 34199977, 2021). "Targeting both GLP-1 and insulin secretion with a SSTR5 antagonist could perhaps be an advantage in the treatment of hyperglycemia in humans." (PMID 33434183, 2021). "Indeed, the SSTR5:SSTR2 activation ratio has been hypothesized to be the main driver of pasireotide-induced hyperglycaemia." (PMID 26906713, 2016). "The stimulation of pancreatic SSTR-5 suppresses insulin secretion, which, combined with negative effects on incretin hormone secretion, leads to pasireotide-induced hyperglycemia." (PMID 40283624, 2025). "SSTR5 antagonist alone is effective at lowering blood glucose when glucose is delivered orally but not intraperitoneally, which is in line with our findings that triple treatment protects against olanzapine-induced glucose intolerance but not olanzapine-induced hyperglycemia." (PMID 36937886, 2023).
insulinomas (8 papers, 2014 to 2026). "SSTR5 is the second most expressed receptor in insulinomas, and pasireotide, an analog with higher affinity for SSTR5, has been associated with a median progression-free survival of 11 months." (PMID 40648766, 2025). "Of the five subtypes of SSTRs (named SSTR1–5), SSTR2 and SSTR5 are most commonly expressed in insulinomas (∼70%)." (PMID 25755880, 2015). "The inadequate control of insulin secretion by somatostatin analogs is probably a consequence of the low expression of SSTR2 and SSTR5 in insulinomas, which also explains the reason for the low percentage of SPECT scintigraphy-positive tumors." (PMID 25298880, 2014). "Recent studies show that RPL-1980 abolishes GLP-1-stimulated PDX-1 expression in mouse insulinoma β-TC6 cells, indicating that SSTR5-mediated somatostatin signaling is a potential novel negative regulator for PDX-1 expression." (PMID 25009500, 2014). "Moreover, SSTR5 P335L prevents the inhibitory effects of SSTR5 agonist RPL-1980 on cell proliferation of Mia PaCa-2 cells and glucose-stimulated insulin secretion from mouse insulinoma β-TC6 cells, while wild-type SSTR5 enhances the effects." (PMID 25009500, 2014).
meningioma (7 papers, 2017 to 2025). A generally slow growing tumor attached to the dura mater. "The distribution of SSTR1, SSTR4 and SSTR5 in feline meningiomas was similar to that of human meningiomas." (PMID 39011594, 2024). "This is in line with the results of our previous study, where we were able to show that the expression of SSTR5 is lower in WHO grade III meningiomas." (PMID 34601710, 2022). "For SSTR5, the differences were more pronounced with 5.7 for spinal meningiomas, while skull base and convexity/falx locations reached a mean score of 4.5 and 4.9 (p < 0.0001)." (PMID 33899156, 2022). "Our recent retrospective analysis has demonstrated that SSTR1 and SSTR5 are also highly expressed in many meningiomas." (PMID 35566491, 2022). "Other SSTRs have also been detected in meningiomas, and a higher expression of SSTR5 was found in WHO grade 2 meningiomas, but their relationship to histopathological features and tumor grade are sparsely described." (PMID 34830858, 2021). "Regarding SSTR5, both nuclear and cytoplasmatic immunoreactivity were detected in all positive meningiomas." (PMID 34830858, 2021). "Besides podoplanin, somatostatin receptors, especially somatostatin receptor 2 (SSTR-2) and somatostatin receptor 5 (SSTR-5), are frequently expressed in meningiomas and are promising targets for malignant meningioma." (PMID 40430568, 2025). "• RNA analysis showed SSTR1, SSTR2 and SSTR5 expressions in canine meningiomas." (PMID 39011594, 2024). "SSTR5 has a higher prevalence in canine meningiomas than in human meningiomas (33%–67%)." (PMID 39011594, 2024). "Therefore, we analyzed the distribution of 5 somatostatin receptors (SSTR1, SSTR2A, SSTR3, SSTR4, SSTR5) in a large meningioma cohort including patients suffering from NF2 and higher grade meningiomas." (PMID 33899156, 2022). "In feline meningiomas (n = 12), RNA expression of SSTR1, SSTR4, SSTR5 and SSTR2 was detected in 91%, 46%, 46% and 36% of samples, respectively; SSTR3 was not expressed." (PMID 39011594, 2024). "The recurrent meningioma expressed SSTR1, which the first meningioma also expressed, and additionally expressed SSTR5." (PMID 39011594, 2024). "In canine meningiomas (n = 7), RNA expression of SSTR1, SSTR2 and SSTR5 was detected in all samples; SSTR3 RNA expression was detected in only 33% of samples." (PMID 39011594, 2024). "This large cohort also showed strong expression of SSTR1 and SSTR5 and different expression patterns within various clinical subgroups, such as neurofibromatosis type 2 and WHO grades II and III meningiomas." (PMID 35566491, 2022). "Immunohistochemical staining for SSTR5 was scored similar for grade I and II tumors, and lower values were seen for grade III meningiomas (p = 0.0003)." (PMID 33899156, 2022). "In 2015, a similar but contrary context was described for SSTR5, in the largest study on SSTR expression in meningiomas so far by Silva and colleagues." (PMID 34601710, 2022). "• Feline meningiomas exhibited SSTR1, SSTR4, SSTR5 and SSTR2 expressions." (PMID 39011594, 2024). "Meningiomas that were treated with radiotherapy before resection had significant lower scores for SSTR1 (5.4 compared to 6.6, p = 0.0007) and SSTR5 (4.3 compared 4.9, p = 0.0340), while expression of SSTR2A, 3, and 4 were similar to tumor tissue that did not receive radiotherapy." (PMID 33899156, 2022).
prostate carcinoma (7 papers, 2014 to 2023). A carcinoma that arises from epithelial cells of the prostate gland. "Previous observations were made that the slice variant of SSTR5, namely sst5TMD4, is highly expressed at the level of protein and mRNA in prostate cancer and can govern some pathophysiological roles as a biomarker and/or therapeutic intervention in patients with worse prognosis." (PMID 38203605, 2023). "SSTR2 is preferably expressed in the normal prostate, while SSTR1 and SSTR5 are expressed in prostate cancer." (PMID 33586406, 2021). "Hypermethylation of SSTR1 gene along with reduced expression was found in head and neck squamous cell carcinoma, and the reversed SSTR5 methylation was shown to up-regulate SSTR5 mRNA expression in prostate cancer." (PMID 26796520, 2016). "Moreover, 5-AZA-dC and TSA treatment increased SSTR5 mRNA expression levels in a castration-resistant prostate cancer cell line." (PMID 33085037, 2021). "For prostate cancer, it was demonstrated that SSTR2 and SSTR5 are mostly expressed, i.e. in 34.8% and 56.5%, respectively." (PMID 33085037, 2021).
pancreatic NETs (6 papers, 2015 to 2024). "The aim of this study is to correlate SSTR-2a and SSTR-5 expression in pancreatic neuroendocrine tumors (PNETs) with survival." (PMID 26447992, 2015).
diabetes (5 papers, 2018 to 2026). "As SSTR5 is expressed in pancreatic β‐cells and intestinal L‐cells, studies have suggested that SSTR5 regulates glucose tolerance through insulin and incretin secretion, thereby having a prominent role in diabetes." (PMID 36585794, 2023). "In the present study, we provide evidence that PDAC-associated diabetes is distinguished by a global downregulation of key islet hormones (INS, GCG) as well as β-cell-enriched transcription factors such as MAFA and PAX4, and hormone receptors such as GCGR, SSTR3 and SSTR5." (PMID 40244011, 2025). "Of the major islet hormones only expression of SST was not significantly reduced in diabetes-associated PDAC, although both Somatostatin Receptor 3 (SSTR3) and SSTR5 which allow paracrine signaling of somatostatin to surrounding α- and β-cells were decreased." (PMID 40244011, 2025).
pancreatic cancer (5 papers, 2012 to 2023). "Another study showed that various mutations on SSTR5 tail inhibits the anti-proliferation of SSTR5 on pancreatic cancer cells." (PMID 36774350, 2023). "Previous researches report that SSTR5 agonist somatostatin analog AN-238 significantly suppresses the proliferation of pancreatic cancer cells both in vitro and in vivo." (PMID 36774350, 2023). "Another study showed that various mutations in the tail of SSTR5 inhibit the anti-proliferation of SSTR5 in pancreatic cancer cells." (PMID 36774350, 2023). "mRNA expression of SSTR2 and SSTR5 has been shown in different pancreatic cancer cell lines including Panic-1, MIA PaCa-2 and Hs 766T." (PMID 38203605, 2023). "In vitro and in vivo studies suggest that SSTR1, SSTR2, and SSTR5 suppress the growth of pancreatic cancer." (PMID 37900156, 2023). "In this study, we detected the expression of somatostatin receptor subtypes SSTR-2, SSTR-3, and SSTR-5 messenger RNA (mRNA) from 108 cases of cancer tissue and adjacent tissue in patients with pancreatic cancer using RT-PCR method." (PMID 25890201, 2015). "The expression of somatostatin receptor subtypes SSTR-2, SSTR-3, and SSTR-5 messenger RNA (mRNA) in 108 cases of cancer tissue and adjacent tissue in patients with pancreatic cancer was detected by reverse transcriptase polymerase chain reaction (RT-PCR)." (PMID 25890201, 2015). "There is less difference in the rate of SSTR-5 mRNA expression in pancreatic tumor tissue and tumor adjacent tissue, both were low, which is consistent with previous findings." (PMID 25890201, 2015). "SSTR5 is a proven anti-proliferation receptor in pancreatic cells, Previous studies have reported that the SSTR5 agonist somatostatin analogue AN-238 can significantly inhibit the proliferation of pancreatic cancer cells in vitro and in vivo." (PMID 36774350, 2023). "Based on published literatures and our above results, we hypothesize that SSTR5 palmitoylated by ZDHHC5 would downregulate its inhibitory effect leading pancreatic cancer cell’s proliferation." (PMID 36774350, 2023). "Taken together, we hypothesized that antagonizing ZDHHC5-mediated palmitoylation on the cytoplasmic tail of SSTR5 may represent a more efficacious approach for the treatment of pancreatic cancer." (PMID 36774350, 2023). "We hypothesized that antagonizing ZDHHC5-mediated palmitoylation on the cytoplasmic tail of SSTR5 may represent a more efficacious approach for the treatment of pancreatic cancer." (PMID 36774350, 2023). "Therefore, in relation to drug receptor binding affinity and organ-specific aspects, we studied SSTR-2, SSTR-3, and SSTR-5 expression in the pancreatic cancer." (PMID 25890201, 2015). "Tissue specimens of pancreatic cancer displayed decreased mRNA expression for SSTR2 and SSTR5 when compared with the normal tissue adjacent to the carcinoma." (PMID 38203605, 2023). "Our study is aimed at exploring the cause from different therapeutic effects of somatostatin and its analogs on human pancreatic cancer and their relationship between changes of SSTR-2 gene expression and expression of SSTR-2, SSTR-3, and SSTR-5 genes." (PMID 25890201, 2015).
breast carcinoma (4 papers, 2006 to 2023). "Most importantly, the overexpression of SSTR5’s truncated form, sst5TMD4, in breast cancer model increases the pro-angiogenic factors, as well as the number of blood vessels, and is associated with the proliferation of and treatment response to SST analogs." (PMID 38203605, 2023). "We further anticipate such a possibility of heterodimerization between SSTR1 and SSTR5 and, additionally, between SSTRs and ErbBs in breast cancer cells." (PMID 16519802, 2006). "Predominant SSTR1 expression and weak SSTR5 expression in breast cancer cells may help explain their poor sensitivity to hormonal therapy." (PMID 16519802, 2006). "In human breast cancer cells, SSTR1 and SSTR5 subtypes heterodimerize with epidermal growth factor receptor and modulate the downstream MAPK pathway in an agonist-dependent manner." (PMID 38203605, 2023).
TSHomas (4 papers, 2017 to 2025). "However, in thyrotroph adenomas, it has been reported that the presence of SSTR5 is correlated with both in vivo and in vitro response to SSA." (PMID 32706866, 2020).
carcinoid tumor (3 papers, 2014 to 2024). A slow growing neuroendocrine tumor, composed of uniform, round, or polygonal cells having monotonous, centrally located nuclei and small nucleoli, infrequent mitoses, and no necrosis. "Typical carcinoid tumors usually have high concentration of somatostatin receptors among which octreotide binds with higher affinity to SSTR-2 and SSTR-5." (PMID 25431598, 2014). "Treatment of recently established PNET cell line NT-3 and pulmonary typical carcinoid cell line H727 with 10 μM BYL719 for 48 h induced mRNA expression of SSTR2, but not SSTR5, two genes related to neuroendocrine differentiation." (PMID 38375032, 2024).
glioblastoma (3 papers, 2019 to 2025). The most malignant astrocytic tumor (WHO grade IV). "A clear downregulation of the whole somatostatin/cortistatin-system (except for SSTR5) in glioblastoma vs. non-tumour brain samples was demonstrated, with high discriminatory capacity." (PMID 40268793, 2025). "In the majority of glioblastomas, the expression of SSTR2 is negative (the most commonly expressed is SSTR5)." (PMID 31432278, 2019).
glioma (3 papers, 2021 to 2023). A benign or malignant brain and spinal cord tumor that arises from glial cells (astrocytes, oligodendrocytes, ependymal cells). "CXCL10, CCL13, SAA1, and CCL27 were more highly expressed in elderly, high‐grade, 1p19q non‐codel, IDH‐wildtype glioma patients, while SSTR5, CCL21, and HTR1A expressions were low in these malignant clinicopathological features of gliomas." (PMID 33503296, 2021). "Notably, 5/14 OPR-DEGs, including TDH, SSTR5, HMGN5, LGR6, and SEL1L3, also have different expressions between high-risk patients and low-risk patients in the TCGA PTEN-wt subgroup (p < 0.001), suggesting that they are associated with the prognosis of PTEN-wt glioma." (PMID 34336645, 2021).
hepatocellular carcinoma (3 papers, 2013 to 2025). A malignant tumor that arises from hepatocytes. "The mechanism was thought to be the interaction of pasireotide with a high proportion of somatostatin receptor type 5 (SSTR5) expressed in hepatocellular carcinoma, leading to the lowering of IGF-2 levels." (PMID 41209155, 2025). "Similar to the results for the HCC samples, the most prominent SSTR in the hepatoblastoma/hepatoma cell lines was SSTR5, and (as in the tumors) expression of SSTRs in hepatoblastoma/hepatoma cell lines was weak compared with the expression levels observed in NCI-H69 and BON-1 cells." (PMID 29282035, 2017).
hypercortisolism (3 papers, 2020 to 2025). "In our study, the expression of SSTR2 or SSTR5 was detected in cases 1, 7, and 8, in which SSA had good effects on the control of hypercortisolism." (PMID 35265125, 2022).
lung NETs (3 papers, 2018 to 2024). "It has been previously suggested that circulating levels of SSTR5 could be a potential biomarker for lung NETs." (PMID 29467960, 2018).
melanoma (3 papers, 2022). A malignant, usually aggressive tumor composed of atypical, neoplastic melanocytes. "Furthermore, this core-DEG also contained two neuronal genes, NPTXR and SSTR5, suggesting that melanoma stem cell properties might also have a role in ICI therapy resistance." (PMID 35269844, 2022).